TRBD1 (T cell receptor beta diversity 1)
Description:
D region of the variable domain of T cell receptor (TR) beta chain that participates in the antigen recognition. Alpha-beta T cell receptors are antigen specific receptors which are essential to the immune response and are present on the cell surface of T lymphocytes. Recognize peptide-major histocompatibility (MH) (pMH) complexes that are displayed by antigen presenting cells (APC), a prerequisite for efficient T cell adaptive immunity against pathogens. Binding of alpha-beta TR to pMH complex initiates TR-CD3 clustering on the cell surface and intracellular activation of LCK that phosphorylates the ITAM motifs of CD3G, CD3D, CD3E and CD247 enabling the recruitment of ZAP70. In turn ZAP70 phosphorylates LAT, which recruits numerous signaling molecules to form the LAT signalosome. The LAT signalosome propagates signal branching to three major signaling pathways, the calcium, the mitogen-activated protein kinase (MAPK) kinase and the nuclear factor NF-kappa-B (NF-kB) pathways, leading to the mobilization of transcription factors that are critical for gene expression and essential for T cell growth and differentiation. The T cell repertoire is generated in the thymus, by V-(D)-J rearrangement. This repertoire is then shaped by intrathymic selection events to generate a peripheral T cell pool of self-MH restricted, non-autoaggressive T cells. Post-thymic interaction of alpha-beta TR with the pMH complexes shapes TR structural and functional avidity.
Synonyms: TCRBD1
Tractability: Antibody: UniProt places it where antibodies can reach, with medium confidence; its Gene Ontology location is reachable by antibodies, with medium confidence.
Gene: T-cell receptor diversity (D) gene on chromosome 7 (142,786,213 to 142,786,224, forward strand). Ensembl gene ENSG00000282431.
Subcellular location: Cell membrane
Gene Ontology:
Cellular component: plasma membrane
Diseases named in the same sentence as TRBD1 in open-access papers:
TRBD1 is named in the same sentence as 2 diseases in open-access papers, as found by Europe PMC text mining. Sharing a sentence is not in itself a finding about the gene and the disease. The quoted sentences say what the papers report.
infection (1 paper, 2025). The state of being infected such as from the introduction of a foreign agent such as serum, vaccine, antigenic substance or organism. "Several common TRA and TRB pairs, such as TRAV1-2/TRAJ33, TRAV21/TRAJ49, TRBV6-4/TRBD2/TRBJ2-3, and TRBV5-1/TRBD1/TRBJ2-7, were consistently detected from the primary infection (PI) through the convalescent phase (HC) and into the reinfection phase (RI)." (PMID 41209021, 2025).
TRBD1 also shares sentences with these, for which no sentence is quoted: COVID-19 (1 paper).